KIF14 (kinesin family member 14)
Diseases named in the same sentence as KIF14 in open-access papers (continued):
Sharing a sentence is not in itself a finding about the gene and the disease.
cancer (continued). "In PDAC, KIF14 was reported to be associated with perineural invasion 37 with KIF14 found to be upregulated in PDAC and cancer cells invading the perineural niche." (PMID 33033514, 2020). "The advent of this model raised the appealing possibility of exploring Kif14’s cancer-promoting effects in animals." (PMID 30385851, 2018). "Consistent with this, knockdown of KIF14 decreases tumour cell and xenograft growth, while overexpression promotes growth both of cancer cells, and also normal mammary epithelial cells." (PMID 30385851, 2018). "We further performed a summary for KIF14 gene expression extracted from to the Oncomine database, a cancer microarray database and Integrated Data-Mining Platform." (PMID 28525372, 2017). "The involvement of these cancer related pathway indicated that KIF14 has functional role in carcinogenesis of PCa." (PMID 28525372, 2017). "The 9-gene group includes KIF14, a known oncogene associated with aggressive tumor qualities in many cancers, linking HDAC11 epigenetic regulation to the hallmarks of aggressive cancers." (PMID 28252645, 2017). "Kinesin family member 14 (KIF14) is a member of kinesin family proteins which have been found to be dysregulated in various cancer types." (PMID 27128470, 2016). "KIF14 has been found to be up-regulated in various cancer types and is involved in tumorigenesis process partially due to its function in cytokinesis and chromosome segregation." (PMID 27128470, 2016). "Tumor KIF14 expression levels are independently predictive of poor outcome, and in cancer cells KIF14 can modulate metastatic behavior by maintaining appropriate levels of cell adhesion and migration proteins at the cell membrane." (PMID 24626475, 2014). "Understanding KIF14's regulation in cancer cells is crucial to the development of effective and selective therapies to block its tumorigenic function(s)." (PMID 24626475, 2014). "miRNA expression analysis of primary OvCa tumors and cell lines revealed three putative regulators (miR-93, miR-144 and miR-382) of KIF14 expression that have documented roles in tumorigenesis in cancer cells." (PMID 24626475, 2014). "Our findings reveal multiple mechanisms of KIF14 upregulation in cancer cells, offering new targets for therapeutic interventions to reduce KIF14 in tumors, aiming at improved prognosis." (PMID 24626475, 2014). "We also dissected the molecular mechanism of KIF14, which mediates the suppression of cancer cell invasion, migration and adhesion." (PMID 23626713, 2013). "The overexpression and silencing of KIF14 also inhibited or enhanced cancer cell migration, invasion and adhesion to the extracellular matrix proteins laminin and collagen IV." (PMID 23626713, 2013). "Immunochemistry indicated that the expression levels of KIF14 were negatively correlated with cancer metastasis in patients." (PMID 23626713, 2013). "However, while kinesins have been implicated in cancer progression, further studies are required to elucidate the precise molecular mechanisms underlying KIF11 and KIF14 expression in EC." (PMID 40075652, 2025). "Studies reported the carcinogenic effects of KIF14 in several cancers." (PMID 40374610, 2025). "Understanding the mechanisms by which KIF11 and KIF14 influence cancer progression could inform the development of targeted therapies aimed at modulating their expression or function, potentially improving prognoses for patients with various malignancies." (PMID 40075652, 2025). "KIF14, NUF2, and ESPL1, have been associated with poorer prognosis in various cancers." (PMID 39766071, 2024). "Our results demonstrated that KIF14 was upregulated in a variety of cancers, including LUAD." (PMID 36227151, 2022). "KIF14 has been proven by numerous researchers to be an important oncogene in many cancers." (PMID 35439960, 2022). "In addition, ANLN expression was strongly associated with that of DEPDC, KIF14, KIF23, RACGAP1, and CKAP2L genes across cancers." (PMID 35340220, 2022).
cancer (continued). "Knocking-down of KIF14 could result in the failure of cytokinesis and inhibition of cancer cell growth, while overexpression of KIF14 induced cancer cell proliferation." (PMID 36227151, 2022). "KIF14 overexpression is a significant prognostic biomarker in various cancers." (PMID 36227151, 2022). "Therefore, as KIF14 becomes an increasingly important target for cancer therapy and prognostic monitoring markers, it is crucial to understand the mechanisms regulating its gene." (PMID 35439960, 2022). "KIF14 is confirmed to promote cancer cell proliferation and contribute to chemoresistance." (PMID 35873497, 2022). "Interestingly, the genes CDC20, CDCA8, MYBL2, C1QTNF6, CEP55, CDK1 and KIF14 were found to be more universal/common, since they mark multiple types of cancers not only in prognosis but also in diagnosis." (PMID 32489468, 2020). "The oncogene KIF14 is activated in several cancers, including HCC." (PMID 33203790, 2020). "KIF14 is a cancer gene with broad relevance to epithelial and neuronal cancers." (PMID 30385851, 2018). "KIF14 was elevated in all cancer cell lines except for Hs578T and T47D." (PMID 28061449, 2017). "Further analysis of these samples showed that expression of KIF14 mRNA and protein exceed the levels expected based on the copy number gain alone, suggesting an up-regulation in the transcriptional control in cancer cells versus their respective normal counterparts." (PMID 24626475, 2014). "KIF14 (kinesin family member 14) is a mitotic kinesin and an important oncogene in several cancers." (PMID 24626475, 2014). "The depletion of one of the KIFs, KIF14, might delay the metaphase-to-anaphase transition, resulting in a binucleated status, which enhances tumor progression; however, the exact correlation between KIF14 and cancer progression remains ambiguous." (PMID 23626713, 2013). "Because the expression of KIF14 was negatively correlated with metastasis in patients, we next investigated whether KIF14 affected cancer cell metastasis." (PMID 23626713, 2013). "We further investigated whether the protein expression levels of KIF14 in tumor specimens were negatively correlated with cancer metastasis in patients." (PMID 23626713, 2013). "Because KIF14 inhibited cell migration, invasion and adhesion in vitro and cancer metastasis in vivo, we wanted to determine whether changes in the motor function in cells could lead to physiological changes." (PMID 23626713, 2013). "However, only 6 of the 59 patients with high KIF14 expression developed cancer metastasis (P<0.0001)." (PMID 23626713, 2013). "The role of KIF14 in cancer progression has been discussed in recent years." (PMID 23626713, 2013). "Over-expression of KIF14 by RT-PCR was seen inretinoblastoma and numerous other cancer types including breast, lung, larynx, andhepatocellular carcinoma where numerous studies suggested thatKIF14 might have oncogenic potential." (PMID 21079744, 2010). "Interestingly, KIF14 has been reported to act as either an oncogene or a tumor suppressor depending on the cancer type, and its precise role in EC remains unclear." (PMID 40075652, 2025). "Thus, KIF14 might inhibit tumor growth and cancer metastasis through controlling the recruitment of adhesion molecules to the cell membrane to modulate cell adhesion, migration and invasion." (PMID 23626713, 2013). "We found positive LASSO coefficients for the genes CDKN2A, EGLN3, KIF14, and RECQL4 that were upregulated in cancer compared with normal samples." (PMID 36552262, 2022). "The Kaplan-Meier (K-M) survival analysis was conducted to assess the correlation between KIF14 expression and survival outcomes (PFS and OS) in pan-cancer according to the TCGA database." (PMID 36227151, 2022). "Our results demonstrated that KIF14 was significantly correlated with TMB, MSI and immune checkpoint-related genes in various cancers." (PMID 36227151, 2022).
cancer (continued). "KIF4A, KIF14 and KIF20A are shown to be overexpressed across many human cancer types suggesting a link between expression levels and overall survival." (PMID 30991738, 2019). "To examine the changes in cancer progression in vitro and in vivo, we established stable Flag-tagged KIF14-expressing cell lines from CL1-5 cells and KIF14-silenced CL1-0 cells, and the protein expression pattern was confirmed through immunoblotting." (PMID 23626713, 2013). "Furthermore, inhibiting KIF14 and KIF18B has been explored in other cancers, and future functional studies and drug sensitivity analyses will be essential to evaluate their potential as therapeutic targets." (PMID 40405535, 2025). "The first were tightly regulated, through MELK, BRCA2, KIF14, BUB1, and TOP2A, by five TFs (NFE2L3, RUNX1, RUNX2, BHLHE40, and the aging cancer-specific SOX11), two LncRNAs (ST7OT1 and CDKN2BAS), and four miRNAs (miR-21-5p, miR-363-3p, miR-873-5p, and miR-138-1-3p)." (PMID 37191407, 2023). "According to our results, and unlike the data published for other examined cancers, KIF14 protein expression was downregulated in CRC tissues compared to the adjacent noncancerous tissues." (PMID 34575892, 2021). "It is, therefore, not surprising that the aberrant expression of KIF11 or KIF14 disturbs centrosome separation, bipolar spindle assembly, chromosome segregation, and cytokinesis, which eventually can result in GIN and the development and/or progression of a broad spectrum of cancers." (PMID 34208606, 2021).
tumor (56 papers, 2009 to 2026). "As a microtubule-based motor protein, KIF14 is involved in growth and cell motility in tumor cells and is associated with poor clinical outcome, which causes the response to radiation therapy." (PMID 41602310, 2026). "This study reveals that ncRNAs-mediated overexpression of KIF14 is associated with tumor immune infiltration and unfavorable prognosis in LUAD." (PMID 36227151, 2022). "The results indicated that lncRNAs- and miRNAs-regulated overexpression of KIF14 was associated with tumor immune infiltration and unfavorable prognosis in patients with LUAD." (PMID 36227151, 2022). "High-expression of KIF14 in LUAD was associated with pathological tumor stage, N stage and unfavorable prognosis." (PMID 36227151, 2022). "We aged a cohort of Kif14-overexpressing transgenic mice and wild-type littermates and documented survival, cause of death, and tumour burden." (PMID 30385851, 2018). "KIF14 expression was positively associated with high tumour stage (P=0.0044), lymph node metastasis (P=0.0034) and chemoresistance (P<0.0001)." (PMID 27128470, 2016). "Furthermore, upregulation of KIF14 in LUAD was positively correlated with tumor mutation burden, microsatellite instability, immune checkpoint-related gene expression, immune cell biomarkers, and tumor immune cell infiltration." (PMID 36227151, 2022). "We subsequently hypothesized that Kif14 overexpression might similarly predispose mice to spontaneous tumours." (PMID 30385851, 2018). "Whether miR93 plays a role in modulating cisplatin resistance in primary OvCa tumors remains to be determined, however our results suggest that loss of miR93 may modulate KIF14 mRNA overexpression in primary OvCa tumor cells to promote poor outcome." (PMID 24626475, 2014). "The project highlights the use of exosomal miRNA as a therapeutic biomarker for suppressing tumor growth and angiogenesis through inhibition of KIF‐14." (PMID 39739455, 2025). "In GC, elevated level of KIF14 was reported to facilitate tumor growth and correlated with advanced tumor stage, tumor-node-metastasis (TNM) classification, and the presence of metastasis." (PMID 40374610, 2025). "In terms of mechanism, tRF-29 played the tumor suppressor role in GC by silencing KIF14 expression and then modulated the AKT pathway." (PMID 40374610, 2025). "Subsequent K-M survival analysis of 102 HCC patients associated high KIF14 expression with poor DFS and late tumor grade and stage, indicating the potential prognostic value of KIF14 in HCC." (PMID 38433242, 2024). "High-KIF14-expressing cells have recently been shown to help form torpedo-like invasive complexes at the tumor–healthy cell interface, with cells expressing the most KIF14 being associated with high metastatic potential." (PMID 39409999, 2024). "KIF11, KIF23, and KIF14 are motor proteins involved in mitosis and intracellular transport that can influence tumor growth and spread, possibly affecting recruitment and localization of immune cells within TME." (PMID 39083127, 2024). "The suitable gene, KIF14, is highly expressed in ccRCC and promotes tumor cell proliferation, migration, and invasion." (PMID 37711200, 2023). "As per our analysis, KIF14 was highly expressed in ccRCC and in patients with higher KIF14 expression levels, the tumor was in a more advanced stage and the prognosis was worse." (PMID 37711200, 2023). "Taking differential expression, correlation and survival analyses into consideration, hsa-miR-101-3p was identified as the most promising upstream binding tumor suppressive miRNA of KIF14." (PMID 36227151, 2022). "The upregulated kinesin family member gene KIF14 is a mitotic kinesin and plays an essential role in tumor development." (PMID 36552262, 2022). "The results showed that KIF14 was positively related to advanced tumor stage (p = 0.021) and lymph node metastasis (p = 0.014)." (PMID 36227151, 2022).
tumor (continued). "High expression of KIF14 was positively related to advanced tumor stage, N stage, uncontrolled disease, smoking history and male." (PMID 36227151, 2022). "When analyzed as continuous variables, a significant increase in staining intensity was found for KIF11 and KIF14 in tumor tissue compared to normal adjacent tissue (both p < 0.0001, Mann–Whitney test)." (PMID 34208606, 2021). "Agminated transcription factor ETS1 would induce angiogenesis and neoplastic cell migration to contribute to tumor progression through upregulating KIF14 expression." (PMID 34712225, 2021). "KIF11 and KIF14 staining was localized to the cytoplasm and to the cytoplasm and/or membrane of tumor cells, respectively." (PMID 34208606, 2021). "In the case of KIF14, tumor tissues demonstrated cytoplasmic labeling but accompanied by nuclear or membranous staining in some CRC samples (n = 28/86, 32.56% and n = 12/86, 13.95%, respectively)." (PMID 34575892, 2021). "In turn, mRNA levels of KIF11 and KIF14 were markedly elevated in tumor tissues compared to normal tissues, and this coincided with adverse prognosis, even after adjusting for multiple confounders." (PMID 34208606, 2021). "We found 260 DEGs (p < 0.05) including 105 upregulated and 155 downregulated genes between KIF14-positive and KIF14-negative tumor cells located in torpedo-like structures." (PMID 32679794, 2020). "KIF14 also participates in modulating components of adhesion on the tumor cell surface, regulating migration and invasion through Rap1a-Radil signaling, thereby promoting cell motility during metastasis." (PMID 33033514, 2020). "Among these, RACGAP1, RARRES3, TPX2, MMP28, GPR87, and KIF14 were upregulated and positively associated with poor survival, whereas TSPAN7 was downregulated and identified as a tumor suppressor." (PMID 33033514, 2020). "Consistent with the results of integrated analysis, mRNA expression of RACGAP1, RARRES3, TPX2, MMP28, GPR87, and KIF14 was significantly upregulated in PDAC tumor tissues, whereas TSPAN7 was significantly downregulated." (PMID 33033514, 2020). "The expression level of KIF14 has been reported to be increased in many tumour types, such as glioma, lung cancer, hepatocellular carcinoma, ovarian cancer, breast cancer, and laryngeal carcinoma, compared to normal tissues." (PMID 31139021, 2019). "To further confirm that KIF14 was regulated by UTX in CRC, we examined the expression of UTX and KIF14 in xenograft tumours using immunohistochemistry (IHC) staining." (PMID 31139021, 2019). "Here, we report the effects of Kif14 overexpression on tumour formation in a population of otherwise normal mice allowed to live out their lifespans." (PMID 30385851, 2018). "Multiple animals bore more than one tumour type at time of death: seven Kif14 Tg mice had two types of tumours and one Kif14 Tg mouse had three distinct types of tumours." (PMID 30385851, 2018). "KIF14 was also found to regulate adhesive components on the tumor cell surface influencing migratory and invasive properties that promote cell motility during metastasis." (PMID 28191313, 2017). "KIF14 is localizes to the central spindle during late phase mitosis and its inhibition in tumor cells results in cell cycle arrest and the formation of binucleated cells." (PMID 28191313, 2017). "Our results showed that significantly higher levels of KIF14 were detected in tumour tissues compared with NATs." (PMID 27128470, 2016). "Nonetheless, our data identify multiple mechanisms of KIF14 regulation in OvCa tumors, and provide insight into potentially novel avenues of therapeutic intervention to regulate KIF14 expression in tumor cells." (PMID 24626475, 2014). "We have identified genomic, transcriptional and miRNA regulation as potential mechanisms of KIF14 overexpression in OvCa cell lines and primary tumor tissues." (PMID 24626475, 2014).